ENSG00000259132 (novel protein)
Gene: Protein-coding gene on chromosome 14 (22,946,270 to 22,982,258, reverse strand). Ensembl gene ENSG00000259132.
Genetic constraint (gnomAD): Loss-of-function variants: 10 observed, 23.57 expected, observed/expected ratio (o/e) 0.42, 90% interval 0.26 to 0.72. Missense variants: 166 observed, 216.87 expected, observed/expected ratio (o/e) 0.77, 90% interval 0.67 to 0.87. Synonymous variants: 71 observed, 85.61 expected, observed/expected ratio (o/e) 0.83, 90% interval 0.68 to 1.01.